NHEJ1 (non-homologous end joining factor 1)
Diseases named in the same sentence as NHEJ1 in open-access papers:
NHEJ1 is named in the same sentence as 60 diseases in open-access papers, as found by Europe PMC text mining. Sharing a sentence is not in itself a finding about the gene and the disease. The quoted sentences say what the papers report.
Immunodeficiency (16 papers, 2012 to 2026). Failure of the immune system to protect the body adequately from infection, due to the absence or insufficiency of some component process or substance. "We further extend the knowledge about the immunodeficiency associated with pathogenic variant in NHEJ1 by deciphering the patient’s TCR and B BCR repertoire using next-generation sequencing (NGS)." (PMID 35967585, 2022). "Loss-of-function variants in NHEJ1, which preferentially mediates the repair of DNA double-stranded breaks, are associated with dysmorphic facies and immunodeficiency, and roughly half of the patients demonstrate anemia–either autoimmune or following bone marrow aplasia." (PMID 38002903, 2023). "Therefore, NHEJ1 mutation results in genetic instability, developmental delay, immunodeficiency associated with microcephaly, and increased cellular sensitivity to ionizing radiation." (PMID 32214226, 2020). "In a separate cohort of 27 patients with inherited immunodeficiency disorders, 8 (29.6%) developed FHM associated with NHEJ1 or LYST variants, underscoring the familial clustering of hematologic disorders." (PMID 40047910, 2025). "This case is the fiftieth reported in the literature and the first in Colombia, given the low prevalence of NHEJ1-related immunodeficiency and its difficult diagnosis due to scarce knowledge." (PMID 39836852, 2024). "Cernunnos/XLF deficiency is a rare, severe combined immunodeficiency, inherited in an autosomal recessive pattern (OMIM number: 611290), related to the NHEJ1 gene." (PMID 39836852, 2024). "This manuscript aims to present an extremely rare case of combined immunodeficiency in a twenty-years-old man with non-consanguineous parents and a homozygote variant of the NHEJ1 gene." (PMID 39836852, 2024). "Microcephaly and immunodeficiency are common to DNA ligase IV deficiency (LIG4 syndrome) and severe combined immunodeficiency with microcephaly, growth retardation, and sensitivity to ionizing radiation due to NHEJ1 deficiency (NHEJ1 syndrome)." (PMID 22373003, 2012). "This case is the fiftieth reported in the literature and the first in Colombia, given the low prevalence of NHEJ1-related immunodeficiency and its difficult diagnosis due to lack of knowledge." (PMID 39836852, 2024). "Microcephaly and immunodeficiency are common features in NBS, LIG4 and NHEJ1 syndrome." (PMID 22373003, 2012). "Interestingly, although humans can develop macular colobomas, NHEJ1 variants described in humans manifest as immunodeficiency, microcephaly, and growth delay, and the relationship between the 7.8 kb canine NHEJ1 variant and non-ocular disease states (i.e., immunodeficiencies) is unknown." (PMID 38003037, 2023).
microcephaly (10 papers, 2012 to 2023). A congenital or acquired developmental disorder in which the circumference of the head is smaller than normal for the person's age and sex. "Three patients with T-B-NK + phenotype with microcephaly were diagnosed by NGS: NHEJ1 variant was detected in 2 siblings from the same family and LIG4 in another patient." (PMID 35482138, 2022). "Pathogenic variants in NHEJ1 result mainly in extreme sensitivity to IR, genome instability, failure to thrive, and microcephaly." (PMID 35967585, 2022). "Among them, two groups of excitatory neurons, THEMIS-PLA2G7 and FEZF2-SCN7A, express several PSGs involved in DNA damage response and mutated in patients with microcephaly such as BRCA1, NHEJ1, RNF168, and TOP3A." (PMID 33441416, 2021). "Among those, a number of DNA damage response genes associated with microcephaly in humans such as BRCA1, NHEJ1, TOP3A, and RNF168 show strong signs of positive selection and might have played a role in human brain size expansion during primate evolution." (PMID 33441416, 2021).
combined immunodeficiency (9 papers, 2015 to 2025). A broad classification of inherited disorders presenting at birth that affect both the cell-mediated and humoral aspects of the immune response. "Mutations in the NHEJ1 have been associated with the clinical phenotype of severe combined immunodeficiency with microcephaly, growth retardation, and sensitivity to ionizing radiation (Phenotype MIM # 611291)." (PMID 30898087, 2019). "Mutations in NHEJ1 gene have been associated with severe combined immunodeficiency." (PMID 30898087, 2019). "Pathogenic variants in genes involved in this process, such as the NHEJ1 gene, cause severe combined immunodeficiency syndrome (SCID) along with neurodevelopmental disease and sensitivity to ionizing radiation." (PMID 35967585, 2022). "Considering its major role in the immune system development, deficiency of NHEJ1 gene products manifests with absence of mature T and B lymphocytes, also known as “severe combined immunodeficiency” (SCID)." (PMID 30898087, 2019). "RAG1/2,DCLRE1C,PRKDC,NHEJ1, andLIG4 result in isolated non-syndromic combined immunodeficiency (CID, due to low-T low-B CID) while defects in other genes cause syndromic combined immunodeficiencies (due to the additional roles of these genes in non-immune cells)." (PMID 35713311, 2022).
Fanconi anemia (5 papers, 2017 to 2025). Fanconi anemia (FA) is a hereditary DNA repair disorder characterized by progressive pancytopenia with bone marrow failure, variable congenital malformations and predisposition to develop hematological or solid tumors. "Of these, 16 (48.5%) had DNA-repair deficiencies (DNA-RD), including eight with Fanconi anemia, six with NHEJ1 variants, and two with BRCA2 mutations." (PMID 40047910, 2025). "We identified a unique deletion encompassing exons 6–31 of the FANCA gene in an eight‐year‐old girl with Fanconi anaemia (Patient 16) and a novel mutation in the non‐homologous end joining factor 1 gene (NHEJ1, also termed Cernunnos) (Patient 17)." (PMID 29797310, 2018).
NHEJ1 syndrome (4 papers, 2012 to 2025). "A few patients with Cernunnos-XLF deficiency are described with mutations in NHEJ1, who present with similar physical and neurodevelopmental features, CID with T- and B-lymphocytopenia, isotype class switching defects and recurrent infections." (PMID 27717373, 2016). "The analysis revealed a homozygous canonical splice site variant, c.530-2A > T, in intron 4 of the NHEJ1 gene (NM_ 024782.3); based on the American College of Medical Genetics (ACMG) guidelines this variant was classified as likely pathogenic, leading to the diagnosis of Cernunnos deficiency." (PMID 40047910, 2025).
B cell lymphomas (3 papers, 2019 to 2022).
lymphopenia (3 papers, 2016 to 2022). Reduction in the number of lymphocytes. "Cases in point are, for instance, the progressive lymphocytopenia as well as bone marrow aplasia in some NHEJ1-deficient individuals, which almost certainly can be put down to a premature aging of hematopoietic stem cells." (PMID 35812385, 2022).
anemia (2 papers, 2020 to 2023). A reduction in the number of red blood cells, the amount of hemoglobin, and/or the volume of packed red blood cells. "While anemia responded to intravenous (IV) methylprednisolone pulses in 2 patients (RAG1 and NHEJ1 defect each), pt.42 with STK4 defect received IV rituximab (375 mg/m2 2 doses) for control of AIHA and she did not have further relapse of AIHA for next 1.5 years." (PMID 33628209, 2020).
breast carcinoma (2 papers, 2019 to 2025). "NHEJ1 PTVs were associated with an OR of 2.70 (1.30, 5.61), p = 0.0079, for breast cancer and 17.67 (5.36, 58.24), p = 2.37 × 10−6, for ovarian cancer." (PMID 40073867, 2025). "Of particular interest was NHEJ1, which reached exome-wide significance in ovarian cancer analysis for the Wald test and showed evidence of association with breast cancer." (PMID 40073867, 2025). "The predicted direction of association with contralateral breast cancer risk was uniformly increased for the LIG4, NHEJ1, and XRCC5 genes while uniformly decreased for the XRCC4 and XRCC6 genes." (PMID 31560388, 2019).
colorectal cancer (2 papers, 2018 to 2020). A primary or metastatic malignant neoplasm that affects the colon or rectum. "XLF (NHEJ1) was recently shown to enhance resistance to oxaliplatin and 5-fluorouracil in colorectal cancer cell lines." (PMID 33195430, 2020).
esophageal squamous cell carcinoma (2 papers, 2016 to 2018). Esophageal squamous cell carcinoma (ESCC) is a type of esophageal carcinoma (EC) that can affect any part of the esophagus, but is usually located in the upper or middle third. "It was also recently reported that PC4 knockdown impairs the recruitment of non-homologous end-joining factor 1 (XLF) to DSBs in human esophageal squamous cell carcinoma, effectively radio-sensitizing these cells." (PMID 27374870, 2016).
lymphoma (2 papers, 2019 to 2025). A malignant (clonal) proliferation of B- lymphocytes or T- lymphocytes which involves the lymph nodes, bone marrow and/or extranodal sites. "The remaining 8 (29.6%) patients, including 6 from the same family with NHEJ1 mutations and 2 with LYST mutations, developed secondary MDS (sMDS)/AML or lymphoma, with a family history suggestive of FHM." (PMID 40047910, 2025). "Notably, 6 of 7 patients from the same family (family-1) with homozygous NHEJ1 variants progressed to secondary myelodysplastic syndrome (sMDS), acute myeloid leukemia (AML), or lymphoma." (PMID 40047910, 2025).
Nijmegen breakage syndrome (2 papers, 2018 to 2022). Nijmegen breakage syndrome is a rare genetic disease presenting at birth with microcephaly, dysmorphic facial features, becoming more noticeable with age, growth delay, and later-onset complications such as malignancies and infections. "Microcephaly with bird-like facial dysmorphia may be observed at birth in cases of DNA Ligase IV deficiency (LIG4), Nijmegen breakage syndrome (NBS1), and Cernunnos-NHEJ1 deficiency (NHEJ1)." (PMID 35601409, 2022).
Artemis deficiency (1 paper, 2024). "Sixpatients had ADA deficiency, 3 had IL2RG deficiency, 3 had CD3 Delta deficiency, 2 had Artemis deficiency (affecting DCLRE1C), and 1 each had variants impacting NHEJ1, TRAC, RAC2, and RMRP." (PMID 39062699, 2024).
colon cancer (1 paper, 2020). "To determine the expression pattern of core NHEJ genes in colon cancer, we performed Oncomine analysis for XRCC6 (Ku70), XRCC5 (Ku80), PRKDC (DNA-PKcs), XRCC4 (XRCC4), LIG4 (DNA ligase 4), NHEJ1 (XLF), and PAXX (PAXX/XLS)." (PMID 33195430, 2020). "Intriguingly, we observed that NHEJ1 expression is negatively correlated with PAXX expression, and PAXX was observed to be consistently overexpressed in colon tumors compared to the normal tissues, both at the mRNA and protein levels." (PMID 33195430, 2020). "This analysis revealed upregulation of XRCC5, PRKDC, and PAXX in colon cancer compared to normal colon tissues, while LIG4 and NHEJ1 (XLF) displayed downregulation." (PMID 33195430, 2020). "Our analysis revealed that BRAF mutant colon cancer did not harbor higher NHEJ1 expression compared to BRAF wild type tumors and three NHEJ pathway genes, XRCC5, PRKDC, and LIG4 are indeed lowly expressed in BRAF mutant tumors." (PMID 33195430, 2020).
craniosynostosis (1 paper, 2021). Craniosynostosis is defined as the premature fusion of one or more cranial sutures leading to secondary distortion of skull shape resulting in skull deformities with a variable presentation. "In a 9-month-old female with craniosynostosis and syndactyly, we found a rare 32 kb heterozygous de novo intronic duplication within the NHEJ1 gene (case 1703)." (PMID 34556655, 2021).
diabetes (1 paper, 2016). "Of these, non-homologous end-joining factor 1 (Nhej1) had the highest absolute fold change in expression with both diabetes and treatment." (PMID 27855634, 2016). "Nhej1, a DNA repair gene, showed the highest fold changes of the protein coding genes regulated by P78 treatments (ET, LT) in both stages of diabetes." (PMID 27855634, 2016). "Diabetes induced expression levels of Nhej1 by +32.04 while P78 complete reversed expression by -37.94 fold changes." (PMID 27855634, 2016). "The protective role of P78 in reducing assault on the kidney by diabetes-induced DNA damage, may in turn, result in decreased levels of Nhej1, thus, implicating genotoxicity as a mechanism in renal injury." (PMID 27855634, 2016).
gastric carcinoma (1 paper, 2019). A carcinoma that arises from epithelial cells of the stomach. "Findings from this study include recurrent long-fragment deletions at the viral BART locus, integration of short EBV genomic sequences at the host NHEJ1 gene, and overexpression of lytic genes relative to EBV-associated gastric carcinoma and nasopharyngeal carcinoma." (PMID 31292228, 2019).
Omenn syndrome (1 paper, 2020). An inflammatory condition characterized by erythroderma, desquamation, alopecia, chronic diarrhea, failure to thrive, lymphadenopathy, and hepatosplenomegaly, associated with severe combined immunodeficiency (SCID). "SCID patients had disease-causing mutations in RAG1 or RAG2 (n = 4, two of them presented with Omenn syndrome), IL2RG (n = 4, one of them with confirmed maternal engraftment), NHEJ1 (n = 1), CD3E (n = 1), ADA (n = 1), JAK3 (n = 3, two of them with maternal engraftment) and DCLRE1C (n = 1)." (PMID 32265901, 2020).
retinal detachment (1 paper, 2021). An eye emergency condition which may lead to blindness if left untreated. "In the candidate gene approach, COL9A2, COL9A3, NHEJ1, RS1 and NDP genes were investigated based on their known associations with RD and retinal detachment in dogs and humans." (PMID 33945575, 2021).
thyroid cancer (1 paper, 2020). "Concerning BRAF mutation in thyroid cancer, two reports have demonstrated that BRAF mutation promotes NHEJ activity through upregulation of NHEJ1 and it is also associated with radioresistance." (PMID 33195430, 2020).
cancer (10 papers, 2017 to 2025). A tumor composed of atypical neoplastic, often pleomorphic cells that invade other tissues. "In addition, we also detected multiple PUD risk, cancer-related genes (for example, IHH, GNAS, NHEJ1, JUP and MECOM), which provided potential targets contributing to the different outcomes of PUD or GC." (PMID 38036781, 2023).
tumor (4 papers, 2017 to 2024). "However, NHEJ1 protein levels in line with the Oncomine analysis were observed to be lower in tumor tissues compared to the controls (p < 0.001)." (PMID 33195430, 2020). "Consistent with the Oncomine analysis, comparison of all available normal (n = 41) and tumor tissues (n = 469) revealed overexpression of XRCC6, XRCC5, PRKDC, XRCC4, and PAXX in tumors compared to normal tissues, while LIG4 and NHEJ1 displayed lower expression in the tumor tissues." (PMID 33195430, 2020). "This analysis revealed significant upregulation of five genes, (XRCC6, XRCC4, PRKDC, XRCC4, and PAXX) and downregulation of two (LIG4 and NHEJ1) NHEJ pathway genes, in tumor tissues compared to the normal tissues." (PMID 33195430, 2020). "However, analysis of 41 paired normal and tumor tissues revealed significant overexpression of only XRCC5, PRKDC, and PAXX genes in tumor tissues compared to the normal colon (respectively), while LIG4 and NHEJ1 still displayed reduced expression (respectively)." (PMID 33195430, 2020).
hematologic malignancies (2 papers, 2020 to 2025). "In contrast, hematologic malignancies (HM) represented 15.8% of cases in NHEJ1-deficient patients, with a tendency toward MDS/AML." (PMID 40047910, 2025). "Genomic efforts have recently uncovered additional mutations in NHEJ repair genes, Artemis (DNA Cross-Link Repair 1C) and Cernunnos (XLF/NHEJ1), to cause hematological malignancies in anectodal reports." (PMID 33194896, 2020).
genetic diseases (1 paper, 2020). "However, there have been no reports of genetic diseases caused by mutations of core NHEJ genes, including NHEJ1, in birds, and the localization and function of NHEJ1 at DSB sites remain unknown for chicken cells." (PMID 32214226, 2020).
infection (1 paper, 2020). The state of being infected such as from the introduction of a foreign agent such as serum, vaccine, antigenic substance or organism. "Consistent with the infection results, some proteins (ARFP1, F120A, HTF4, NHEJ1, NUFP2, PANX1, and SP130) decreased in abundance but did not produce detectable cleavage products." (PMID 32997711, 2020).
NHEJ1 also shares sentences with these, for which no sentence is quoted: LIG4 syndrome (2 papers); microphthalmia (2); acute myeloid leukemia (1); adenocarcinoma (1); ataxia telangiectasia (1); ataxia-telangiectasia-like disorder (1); Bloom syndrome (1); cataract (1); Cognitive impairment (1); coloboma (1); developmental delay (1); DNA repair disorders (1); dwarfism (1); dysgammaglobulinemia (1); emphysema (1); endometrial cancer (1); Failure to thrive (1); glioblastoma (1); hepatocellular carcinoma (1); leukemia (1); lung carcinoma (1); macular colobomas (1); mucinous adenocarcinoma (1); myelodysplastic syndrome (1); nasopharyngeal carcinoma (1); NBS-like disorder (1); neurodevelopmental disorder (1); neurological disease (1); optic nerve coloboma (1); oral cancer (1).
A further 4 diseases each share a sentence with NHEJ1 in 1 paper.